HERC6 (HECT and RLD domain containing E3 ubiquitin protein ligase family member 6)
Description:
E3 ubiquitin-protein ligase which accepts ubiquitin from an E2 ubiquitin-conjugating enzyme in the form of a thioester and then directly transfers the ubiquitin to targeted substrates.
Synonyms: FLJ20637
Tractability: PROTAC: ubiquitination databases record sites on it.
Gene: Protein-coding gene on chromosome 4 (88,378,739 to 88,443,098, forward strand). Ensembl gene ENSG00000138642.
Subcellular location: Cytoplasm, cytosol
Subcellular location (Human Protein Atlas): Cytosol; Nucleoplasm
Pathways (Reactome):
Immune System: Antigen processing: Ubiquitination & Proteasome degradation
Gene Ontology:
Molecular function: ubiquitin protein ligase activity; ISG15 ligase activity; ubiquitin-protein transferase activity
Biological process: protein ubiquitination; ubiquitin-dependent protein catabolic process; antiviral innate immune response; positive regulation of cGAS/STING signaling pathway; regulation of defense response to virus
Cellular component: cytosol
Genetic constraint (gnomAD): Loss-of-function variants: 69 observed, 63.95 expected, observed/expected ratio (o/e) 1.08, 90% interval 0.89 to 1.32. The upper end of that interval is the gene's LOEUF score, 1.32, which puts it in group 5 of 6, group 1 being the genes least tolerant of losing a copy. Missense variants: 818 observed, 878.61 expected, observed/expected ratio (o/e) 0.93, 90% interval 0.88 to 0.99. Synonymous variants: 313 observed, 319.13 expected, observed/expected ratio (o/e) 0.98, 90% interval 0.89 to 1.08.
Homologues: Orthologues: chimpanzee HERC6 (96% identical), macaque HERC6 (95% identical), pig HERC6 (75% identical), dog HERC6 (72% identical), rabbit HERC6 (71% identical), mouse Herc6 (66% identical), rat Herc6 (63% identical). Paralogues in human: HERC5 (49% identical), HERC3 (38% identical), HERC4 (37% identical), HERC2 (26% identical), UBE3A (20% identical), HECTD1 (18% identical), HECTD4 (18% identical), TRIP12 (17% identical), HECW1 (16% identical), HECW2 (15% identical), HECTD2 (15% identical), HUWE1 (15% identical), and 12 more.
Diseases named in the same sentence as HERC6 in open-access papers:
HERC6 is named in the same sentence as 24 diseases in open-access papers, as found by Europe PMC text mining. Sharing a sentence is not in itself a finding about the gene and the disease. The quoted sentences say what the papers report.
viral infection (6 papers, 2021 to 2025). "Taken together, these data indicate that Herc6 deficiency attenuated viral infection–induced inflammasome activation by inhibiting NLRP3 expression and therefore ameliorated viral infection–induced hyperinflammation in vivo." (PMID 37651190, 2023). "Concordantly, Herc6 deficiency ameliorated NLRP3-dependent inflammation as well as hyperinflammation caused by viral infection." (PMID 37651190, 2023). "Herc6 deficiency attenuates viral infection–caused inflammation." (PMID 37651190, 2023). "Concordantly, Herc6 deficiency ameliorates NLRP3-dependent inflammation and hyperinflammation caused by viral infection." (PMID 37651190, 2023). "HERC6, IFI6, ISG15, and MX1 encode for proteins induced by type I interferons, such as IFN-α, IFN-β, IFN-ω, and are typically produced by host cells in response to viral infection." (PMID 35197051, 2022). "Consequently, HERC5-mediated NLRP3 ISGylation in humans and HERC6-mediated ISGylation in mice enhances NLRP3 inflammasome activation, whereas HERC6 deficiency mitigates the NLRP3-dependent inflammation-related pathologies induced by viral infection." (PMID 40307577, 2025). "A three-gene transcript signature, comprising HERC6, IGF1R, and NAGK, was derived from the discovery cohort of 56 participants with bacterial infections and 27 with viral infections." (PMID 34423323, 2021). "Viral infection, represented by SARS-COV-2 infection, and type I IFNs induced expression of ISG15 and the predominant E3 ISGylation ligases HECT domain- and RCC1-like domain–containing proteins (HERCs; HERC5 in humans and HERC6 in mice)." (PMID 37651190, 2023).
COVID-19 (3 papers, 2023). A disease caused by infection with severe acute respiratory syndrome coronavirus 2. "Herc6 deficiency ameliorated NLRP3-dependent inflammation and ARDS (a direct cause death in patients with COVID-19) in vivo." (PMID 37651190, 2023).
parasite infection (2 papers, 2017 to 2022). "Over both species, the strongest biomarkers for discrimination between viral and bacterial/parasitic disease were UBL1 (PXMP2), IFIT5, GAL3, NFX, VHSVIP4 (VIG4), DEXH (DDX58), unknown CA054694 MX1 RSAD, IFI44A, and HERC6." (PMID 28702195, 2017).
systemic lupus erythematosus (2 papers, 2024 to 2025). An autoimmune multi-organ disease typically associated with vasculopathy and autoantibody production. "Recent studies on systemic lupus erythematosus have revealed the key role of HERC6 in apoptosis and inflammation regulation." (PMID 40520229, 2025). "At the same time, the up-regulation of HERC6 is present in systemic lupus erythematosus (SLE) and promotes inflammation." (PMID 38898455, 2024).
bacterial sepsis (1 paper, 2024). "While Eif2ak2 and Herc6 are implicated in bacterial sepsis, Rnf213 is associated with ubiquitylation of LPS, and Casp1 is a key factor in the inflammatory response in bacterial infection as detected in common upregulation." (PMID 38792580, 2024).
chronic kidney disease (1 paper, 2025). Impairment of the renal function secondary to chronic kidney damage persisting for three or more months. "In the development of a diagnostic model for predicting DCM onset in chronic kidney disease patients, MNS1 and HERC6 emerged as significant model genes." (PMID 40520229, 2025).
liver fibrosis (1 paper, 2023). "We demonstrated a new cellular mechanism by which CVC inhibits ECM accumulation in liver fibrosis by suppressing the hepatic accumulation of inflammatory FSCN1+ macrophages and HERC6+ neutrophils." (PMID 37215993, 2023). "CVC ameliorates ECM deposits and liver fibrosis by suppressing the hepatic accumulation of inflammatory FSCN1+ macrophages and HERC6+ neutrophils." (PMID 37215993, 2023).
psoriasis (1 paper, 2025). An autoimmune condition characterized by red, well-delineated plaques with silvery scales that are usually on the extensor surfaces and scalp. "In addition, 8 genes (DEFB103A, OASL, HERC6, ISG15, MKI67, MX1, MXD1, SCO2) were considered to have statistically significant differences in sensitivity of short-term treatment for psoriasis." (PMID 40560938, 2025).
uterine disease (1 paper, 2022). "Pregnancy regulated genes downstream of AIRE in cows following uterine infection are all upregulated (EIF2AK2, IFI44, HERC6, PARP14, TNFSF10), suggesting the dysregulated expression of these genes could be important for pregnancy establishment following uterine disease." (PMID 35358206, 2022).
infection (5 papers, 2019 to 2024). The state of being infected such as from the introduction of a foreign agent such as serum, vaccine, antigenic substance or organism. "Trim6, Trim56, and Herc6 can also potentiate antiviral immunity by targeting other antiviral effectors in the infection of vesicular stomatitis virus (VSV), pestivirus, and influenza A virus, respectively." (PMID 31057555, 2019). "We observed that vesicular stomatitis virus (VSV, a type of RNA virus) infection and IFN-β stimulation induced HERC6 and ISG15 expression in mouse PMs." (PMID 37651190, 2023).
tumor (4 papers, 2015 to 2024). "From this analysis, the following genes were identified: NAA11, HERC5, DDX60, and HERC6 which were evaluated individually for association with tumor recurrence using the 21 Chinese patient primary tumors." (PMID 26653219, 2015). "HERC6 can be cancer-promoting factors and tumor suppressor genes, depending on the type of cancer." (PMID 38898455, 2024). "The genes Herc6, Kat7, Mef2c, Rbm15, and Shld3 were found to be upregulated in both the right and left tumors of the treated groups, suggesting a coordinated response in tumor inhibition." (PMID 39339213, 2024).
heart disorder (1 paper, 2025). A disease involving the heart and/or pericardium. "Future research should concentrate on the functional validation of HERC6 in heart disorders and assess its viability as a therapeutic target." (PMID 40520229, 2025).
immune dysfunction (1 paper, 2025). "Simultaneously, single-GSEA and immune infiltration analysis indicated immune dysfunction in both DCM and SLE, with both HERC6 and IFI44L significantly associated with immune cell infiltration." (PMID 40808946, 2025).
HERC6 also shares sentences with these, for which no sentence is quoted: cancer (3 papers); influenza (3); bacterial infection (2); atherosclerosis (1); autoimmune disease (1); Autoimmunity (1); breast carcinoma (1); hypopharyngeal cancer (1); lung adenocarcinoma (1); myocardial infarction (1); uterine infection (1).